PCSK9 (proprotein convertase subtilisin/kexin type 9)
Diseases named in the same sentence as PCSK9 in open-access papers (continued):
Sharing a sentence is not in itself a finding about the gene and the disease.
coronary artery disease (continued). "With the wide use of PCSK9 inhibitors in high-risk patients with coronary heart disease (e.g., AMI), researchers are increasingly interested in whether PCSK9 affects myocardial repair after AMI." (PMID 35832650, 2022). "Considering that CIMT is a good surrogate of coronary disease, our data and one previous report suggest that the PCSK9 polymorphism could be a predictive parameter of clinical events of CAD." (PMID 36294964, 2022). "Moreover, another Mendelian study showed PCSK9 genetic variants had smaller associations with risk of ischemic stroke than with risk of coronary heart disease." (PMID 35859596, 2022). "Studies have shown that plasma levels of PCSK9 were associated with circulating LDL-C as well as some other risk factors for coronary diseases, and that high levels of PCSK9 have been found in patients suffering systemic inflammatory response syndrome (SIRS) and sepsis." (PMID 35252378, 2022). "Previously, PCSK9 inhibitors have been shown to reduce major cardiovascular events in secondary prevention and improve adherence and quality of life in high-risk patients with coronary artery disease." (PMID 36280861, 2022). "Moreover, CRP as a marker of inflammation and ASCVD has been positively associated with plasma levels of PCSK9 both in patients with acute coronary syndromes and stable coronary disease." (PMID 34336112, 2021). "In a cross-sectional study on stable coronary disease patients, a positive and independent association was found between plasma PCSK9 levels and platelet count, a reliable marker for various diseases, associated with morbidity, pathophysiology and mortality due to coronary disease." (PMID 34070931, 2021). "Furthermore, platelet count is positively associated with plasma PCSK9 in coronary artery disease (CAD) patients, but the association is lost after adjustment for inflammation, again supporting a role for PCSK9 in inflammation." (PMID 28439730, 2017). "Mutations of PCSK9 leading to reduced expression and or function of PCSK9 are associated with a reduced rate of coronary heart disease, myocardial infarction and overall cardiovascular events, an effect being more pronounced in black as compared to white subjects." (PMID 25600226, 2015). "Studies that have shown decreased risk of coronary artery disease for 'loss-of-function' PCSK9 carriers have generated great interest in the development of PCSK9 inhibitors that could improve current dyslipidemic therapies." (PMID 18547436, 2008). "This case–control study explored the associations of novel single nucleotide polymorphisms (SNPs) of the PCSK9 gene with coronary artery disease (CAD) (≥ 1 coronary artery stenosis ≥ 50%) and its risk factors in the Han population in Xinjiang, China." (PMID 34075144, 2021). "There are only few clinical studies evaluating the relationships between circulating levels of PCSK9, other circulating determinants of the atherosclerotic risk and a comprehensive description of coronary artery disease (CAD) phenotype." (PMID 31672148, 2019). "Similarly, PCSK9 correlates with CV risk in patients with stable coronary artery disease." (PMID 26799206, 2016). "A series of clinical studies have also shown that PCSK9 inhibition can effectively reduce LDL‐C levels and reduce the risk of cardiovascular events in patients with coronary heart disease." (PMID 41573336, 2026). "The rs11591147 mutation in PCSK9, a loss-of-function variant, was causally linked to reduced LDL cholesterol and attenuated coronary heart disease risk." (PMID 41608459, 2026). "In 165 patients with stable coronary heart disease, moderate aerobic training enhanced epoxy-eicosatrienoic acids, activated the FoxO3a/Sirt6 axis, suppressed PCSK9, and ultimately lowered LDL-C despite ongoing statin therapy." (PMID 40861274, 2025).
coronary artery disease (continued). "In contrast, individuals with loss-of-function (LOF) mutations in the PCSK9 gene have lower serum LDL-C levels, which reduces the risk of coronary heart disease and stroke." (PMID 39139638, 2024). "Our study identified two proteins, PCSK9 and AIDA, linked to HF in patients with coronary heart disease (CHD), and four proteins, PCSK9, SWAP70, NCF1, and RELT, associated with HF in patients receiving antihypertensive medication." (PMID 38383373, 2024). "The FOURIER trial is a cornerstone study that demonstrated the effectiveness of PCSK9 inhibition in patients with stable coronary artery disease." (PMID 38610808, 2024). "To comprehensively investigate potential effects of PCSK9 in relation to ischemic HF, we extended our investigation by conducting additional proteome-wide MR analyses across diverse HF etiologies (ischemic heart disease and essential hypertension)." (PMID 38383373, 2024). "This confirmed that PCSK9 is an attractive target for lowering LDL-C levels and thus reducing the risk of ischemic heart disease." (PMID 38790923, 2024). "PCSK9 for example, which is targeted by approved monoclonal antibodies indicated for coronary heart disease, is predominantly expressed in the liver." (PMID 39434187, 2024). "A recent study on statin naïve coronary artery disease patients showed a relationship between circulating mature PCSK9 and statin hyporesponsiveness in these patients." (PMID 39566851, 2024). "In patients with coronary artery disease undergoing percutaneous coronary intervention (PCI), baseline PCSK9 levels during a 28.4-month follow-up were associated with MACE and mortality." (PMID 38796450, 2024). "A third study by the same study group reported a potential link between PCSK9 and platelet count in patients with coronary artery disease." (PMID 38972879, 2024). "Mediation analysis showed that only three percent of the total genetic association of PCSK9 inhibition with LAAS was potentially mediated through Lp(a) reduction, with similar results for the outcome of coronary artery disease." (PMID 39628323, 2024). "A favorable correlation between PCSK9 levels and fibrinogen levels was also found in patients with stable coronary artery disease; these data show a positive correlation between PCSK9 and the coagulation system." (PMID 37765005, 2023). "In some clinical trials, the correlation between PCSK9 and immune response has been demonstrated in patients with atherosclerotic disease, coronary artery disease, systemic lupus erythematosus, and human immunodeficiency virus (HIV)-infected." (PMID 36970356, 2023). "IVW-MR association between LDL cholesterol mediated by gene HMGCR, PCSK9, NPC1L1 or APOB and coronary heart disease." (PMID 37528862, 2023). "PCSK9 loss-of-function variants have been associated with a reduction in circulating LDL-C levels and risk of coronary heart disease." (PMID 36980904, 2023). "Herein, we reviewed the role of early application of PCSK9 inhibitors in patients with coronary heart disease, especially those with ACS, by summarizing clinical trials and meta-analyses in recent years." (PMID 37200976, 2023). "After treatment with atorvastatin, the expression of the lncRNAs LASER and PCSK9 increased simultaneously both in the peripheral blood mononuclear cells (PBMC) of patients with coronary artery disease (CAD), and in HepG2 cells in vitro." (PMID 36979720, 2023). "In patients with coronary artery disease undergoing percutaneous coronary intervention (PCI), during a follow-up of 28.4 months, baseline PCSK9 levels were associated with MACE and mortality." (PMID 37620933, 2023).
coronary artery disease (continued). "For example, PCSK9 inhibition during coronary artery disease is recognized as an effective therapeutic strategy." (PMID 37860186, 2023). "The effects of PCSK9 inhibitors on plaques have been the focus in the context of the widespread use of lipid-lowering therapy in coronary artery disease." (PMID 37200976, 2023). "When stable coronary artery disease occurs, the proportion of CMs to total monocytes is larger in patients with higher PCSK9 levels." (PMID 36970356, 2023). "Loss of function mutations in PCSK9 have been linked to reduced levels of LDL cholesterol and lower incidences of coronary heart disease." (PMID 37762360, 2023). "For example, a small sample size study in Chinese patients with angiography-proven coronary artery disease (CAD) has shown that the increase of plasma PCSK9 level was associated with the elevation in white blood cell counts (WBCC), fibrinogen and high-sensitivity C-reactive protein (hs-CRP)." (PMID 35252378, 2022). "Two PCSK9 inhibitors, alirocumab and evolocumab, are now FDA-approved to reduce circulating LDL levels and lower all-cause mortality in patients with coronary artery disease." (PMID 35862195, 2022). "PCSK9 levels also correlated positively with fibrinogen levels in patients with stable coronary artery disease." (PMID 35323669, 2022). "Clinical analysis showed that PCSK9 levels correlate with white blood cell count in patients with stable coronary artery disease and PCSK9 affected rheumatoid arthritis and sepsis." (PMID 35832650, 2022). "The model is genetically a novel tool for testing therapeutic interventions in the context of the development and treatment of advanced coronary artery disease, including study about PCSK9 and platelet activation." (PMID 36005422, 2022). "Proprotein convertase subtilisin/kexin type 9 (PCSK9) has been shown to be predictive of cardiovascular outcomes in stable coronary artery disease with diabetes." (PMID 35596184, 2022). "In patients with coronary artery disease and diabetes, the levels of PCSK9 correlate positively with those of TF." (PMID 35323669, 2022). "Study indicated that administration of the PCSK9 inhibitors to statins produced significantly lower rate of CAC progression in patients with coronary artery disease." (PMID 35600486, 2022). "An example of this is found in the contrasting results for LDL cholesterol and coronary heart disease at the PCSK9 gene region and those for LDL cholesterol and Alzheimer disease at the APOE gene region." (PMID 35452592, 2022). "In a cohort of stable coronary artery disease patients, plasma PCSK9 levels were positively correlated with the platelet count and plateletcrit." (PMID 36324757, 2022). "A relationship between PCSK9 plasma levels and total number of circulating platelets has been reported in patients with stable coronary artery disease." (PMID 36324757, 2022). "From a genetic perspective, lower plasma LDL-C levels have been observed in individuals with specific sequence variations in the PCSK9 gene, and these individuals exhibit a lower incidence of coronary artery disease (CAD)." (PMID 36077166, 2022). "In patients with stable coronary artery disease, a positive and independent relationship between plasma PCSK9 level and platelet count was observed." (PMID 35806908, 2022). "Quantitative proteomics upon HDL isolated from patients with coronary artery disease (n=172) returned PCSK9 as a core member of the HDL proteome." (PMID 34601896, 2021). "In fact, it has already been shown that the administration of PCSK9 inhibiting antibody therapy to patients with established coronary heart disease (CHD) significantly altered the lipid composition of plasma without affecting inflammatory markers." (PMID 33916712, 2021).
coronary artery disease (continued). "Circulating PCSK9 correlated positively with high sensitive C-reactive protein (CRP) in patients with stable coronary artery disease or acute coronary syndromes." (PMID 33801208, 2021). "Recently, inhibition of PCSK9 has become an effective and safe strategy to treat patients with uncontrolled hyperlipidemia and coronary artery disease." (PMID 34681838, 2021). "Proprotein convertase subtilisin/kexin type 9 (Pcsk9) correlated with incidence and prognosis of coronary heart disease." (PMID 34044829, 2021). "Probably due to this effect, the benefits for patients with diagnosed coronary artery disease using PCSK-9 inhibitors are higher than for patients treated with statins." (PMID 33808697, 2021). "In a study of patients with stable coronary artery disease, fibrinogen levels tended to be higher with high circulating PCSK9 concentration." (PMID 34631822, 2021). "Two prominent examples are PCSK9 and CETP, where loss-of-function mutations are thought to protect from coronary artery disease." (PMID 33575564, 2020). "This risk increase was opposite to, although more modest than, the degree of protection from coronary artery disease predicted by these same methods for PCSK9 inhibition." (PMID 31714636, 2020). "Gain-of-function mutations in PCSK9 cause autosomal dominant hypercholesterolemia, with elevated LDL-C and associated premature coronary artery disease (CAD)." (PMID 32528976, 2020). "Three years later, a second human genetic study reported that PCSK9 loss-of-function mutations reduced low-density lipoprotein cholesterol (LDL-c) and protected against coronary heart disease." (PMID 33050894, 2020). "Gain-of-function mutations in PCSK9 lead to elevated plasma LDL-C levels and accelerated atherosclerosis and premature coronary heart disease." (PMID 30617148, 2019). "Conversely, loss-of-function PCSK9 mutations lead to reduced plasma LDL-C levels and protection from coronary heart disease." (PMID 30617148, 2019). "Loss-of-function mutations in PCSK9 are associated with lower LDL-C and a reduced risk of coronary heart disease (CHD)." (PMID 31664920, 2019). "Proprotein convertase subtilisin/kexin 9 (PCSK9) has been proposed as a novel target for coronary artery disease (CAD)." (PMID 31711505, 2019). "Plasma PCSK9 levels were also positively associated with platelet (PLT) count, another useful indicator associated with CVD, in patients with stable coronary artery disease." (PMID 29343301, 2018). "PCSK9 genetic variants that have large effects on low-density lipoprotein cholesterol (LDL-C) and coronary heart disease (CHD) have prompted the development of therapeutic PCSK9-inhibition." (PMID 29020353, 2018). "Those with variants leading to reduced PCSK9 have lower LDL-cholesterol levels and a reduced risk of coronary heart disease, and this has led to the development of various strategies aimed at reducing circulating PCSK9." (PMID 28025677, 2017). "The recent GLAGOV study tested the effects of PCSK9 inhibition with evolocumab on progression of coronary atherosclerosis in statin-treated 968 patients with coronary artery disease measured by serial intracoronary ultrasonography (IVUS) imaging." (PMID 28439730, 2017). "As for PCSK9 rs11591147, a meta-analysis has been reported that the PCSK9 46 L allele was associated with reductions in LDL-C and ischemic heart disease via pooled three independent studies in 2010." (PMID 28606094, 2017).
coronary artery disease (continued). "In 2005, loss-of-function (LOF) PCSK9 mutations including two nonsense mutations (Y142X and C679X) were discovered, conferring reduced LDL-C and protecting against coronary artery disease." (PMID 28439730, 2017). "Our findings provide new insights into LDL biology and show that targeting PCSK9 using heparan sulfate mimetics is a potential therapeutic strategy in coronary artery disease." (PMID 28894089, 2017). "The purpose of this study was to investigate correlations between serum levels of PCSK9 and apoB-containing atherogenic lipoproteins in patients with coronary artery disease (CAD)." (PMID 27658826, 2016). "In patients with an acute myocardial infarction, the plasma PCSK9 concentration is elevated compared to stable coronary artery disease patients." (PMID 25600226, 2015). "Since elevated LDL-C has long been established as a predominant risk factor for coronary artery disease (CAD), manipulating PCSK9 level would be a promising new treatment strategy." (PMID 25519174, 2014). "A recent study of 243 angiographic cases reported a correlation between the severity of coronary artery disease and plasma PCSK9 levels." (PMID 25180781, 2014). "Deletion of PCSK9, and loss-of-function mutants in humans result in lower levels of circulating LDL-cholesterol and a strong protection against coronary heart disease." (PMID 22848640, 2012). "Notably, rs11591147 in PCSK9 was associated with LDL level and coronary artery disease risk across diverse populations." (PMID 40973818, 2025). "The PCSK9 minipig implanted with BRS may prove a feasible preclinical model for obstructive coronary artery disease." (PMID 40131655, 2025). "Common study focuses include coronary artery disease, lipoprotein (a), or PCSK9 inhibitors." (PMID 40041255, 2025). "Moreover, heterozygote complete PCSK9 LOF variants can primarily protect individuals from cardiovascular events (CVEs) and coronary heart disease (CHD) over a lifetime." (PMID 38185721, 2024). "Of note, since it has been reported that loss-of-function variants of PCSK9 are associated with low circulating levels of LDL cholesterol (LDL-C) and a reduced risk of coronary artery disease, our results suggest a function of CASP11 in promoting LCL-C by enhancing PCSK9." (PMID 39024553, 2024). "Although the exact role of PCSK9 in the formation of atherosclerotic plaque is unclear, several studies have provided strong evidence for PCSK9 blockade in ischemic heart disease and the development of atherosclerotic plaque through an inflammation-mediated process." (PMID 38445291, 2024). "Likewise, there was no clear evidence of heterogeneity (all p > 0.05) or pleiotropy (all p values for intercept > 0.05) regarding HMGCR, NPC1L1 and PCSK9 in erectile dysfunction and positive control coronary heart disease." (PMID 38097781, 2023). "PCSK9 inhibitors are the most potent lipid-lowering therapies available, and they have been used for several years as an adjunct to lipid management in patients with coronary artery disease." (PMID 37200976, 2023). "Natural loss-of-function mutations in PCSK9 and ANGPTL4 resulted in notable protective effects in reduced LDL-cholesterol level and lower risk of premature coronary artery diseases (CAD) over large-population epidemiological studies." (PMID 37285261, 2023). "In these individuals, the minor allele at the R46l locus in PCSK9 did not significantly reduce coronary heart disease or vascular disease risk." (PMID 37378405, 2023).